OR6V1 (olfactory receptor family 6 subfamily V member 1)
Description:
Odorant receptor.
Synonyms: GPR138
Tractability: Antibody: UniProt places it where antibodies can reach, with medium confidence; UniProt predicts a signal peptide or a membrane-spanning region; its Gene Ontology location is reachable by antibodies, with medium confidence.
Gene: Protein-coding gene on chromosome 7 (143,052,341 to 143,053,282, forward strand). Ensembl gene ENSG00000225781.
Subcellular location: Cell membrane
Pathways (Reactome):
Sensory Perception: Expression and translocation of olfactory receptors
Gene Ontology:
Molecular function: olfactory receptor activity; G protein-coupled receptor activity
Biological process: detection of chemical stimulus involved in sensory perception of smell; G protein-coupled receptor signaling pathway
Cellular component: plasma membrane; membrane
Genetic constraint (gnomAD): Loss-of-function variants: 10 observed, 14 expected, observed/expected ratio (o/e) 0.71, 90% interval 0.44 to 1.21. The upper end of that interval is the gene's LOEUF score, 1.21, which puts it in group 5 of 6, group 1 being the genes least tolerant of losing a copy. Missense variants: 350 observed, 401.63 expected, observed/expected ratio (o/e) 0.87, 90% interval 0.8 to 0.95. Synonymous variants: 137 observed, 162.68 expected, observed/expected ratio (o/e) 0.84, 90% interval 0.73 to 0.97.
Homologues: Orthologues: chimpanzee OR6V1 (98% identical), macaque OR6V1 (95% identical), pig OR6V1 (88% identical), dog OR6V1 (86% identical). Paralogues in human: OR6S1 (47% identical), OR6F1 (44% identical), OR6T1 (43% identical), OR6J1 (43% identical), OR6C3 (42% identical), OR6C76 (42% identical), OR6M1 (42% identical), OR6X1 (41% identical), OR2AP1 (41% identical), OR6C65 (41% identical), OR6C75 (41% identical), OR6C4 (40% identical), and 6 more.